MUC1 (mucin 1, cell surface associated)
Diseases named in the same sentence as MUC1 in open-access papers (continued):
Sharing a sentence is not in itself a finding about the gene and the disease.
tumor (continued). "MUC1, human epithelial cell antigen mucin, is recognized in its aberrantly glycosylated form on tumor cells." (PMID 30944835, 2019). "Another IgE specific for the epithelial tumour antigen MUC-1 restricted cancer growth when expressed locally in tumours along with chemoattractant mediators MCP-1 and IL-5." (PMID 31544825, 2019). "As cells transform to a malignant phenotype, expression of MUC1 increases several fold, and glycosylation on tumor synthesized MUC1 is aberrant by reduction of core 2 glycans and a predominance of core 1 glycans." (PMID 31178870, 2019). "In particular, the administration of anti-MUC1 antibodies leads to effective tumor cell killing by antibody-dependent cell-mediated cytotoxicity/phagocytosis (ADCC/ADCP) in part through NK cell and/or macrophage-mediated killing activities." (PMID 31114758, 2019). "As MUC1 is mainly overexpressed in solid tumors, it is important for bispecific agent to penetrate into tumor tissues in order to serve its function." (PMID 30699986, 2019). "After confirming MUC1 as a tumor specific antigen in recurrent HNSCC, for the first time we evaluated the safety and immunological potential of combining the MUC1 peptide/polyICLC vaccine with Tadalafil treatment." (PMID 31214178, 2019). "In order to engage immunocytes with tumor cells, we designed a bispecific aptamer that can bind with both MUC1 and CD16." (PMID 30699986, 2019). "This analysis supports the notion of underglycosylated MUC1 as a tumor specific antigen in patients with recurrent HNSCC." (PMID 31214178, 2019). "The target MTag.MUC1 tumor cells were pretreated with 100 μM indomethacin for 24 hr, and then labeled with 51Cr and plated at effector:target ratios of 100:1." (PMID 31693710, 2019). "Patients who failed oxaliplatin, irinotecan, and 5FU and whose archival tumors stained immunohistochemical (IHC) tumor positive for CK7 or MUC1 received nab‐paclitaxel and gemcitabine therapy with or without cisplatin." (PMID 31102323, 2019). "Circulating Gal-3 can also increase tumor cell adhesion to and migration across the endothelium by interacting with MUC1 on tumor cells, leading to exposure of additional glycosylated ligands including CD44 that bind E-selectin on endothelial cells." (PMID 31195728, 2019). "In this study, a bispecific aptamer was constructed to bind with both MUC1-positive tumor cells and CD16-positive lymphocytes in order to bring the two types of cells together for enhancement of antitumor reaction." (PMID 30699986, 2019). "Apigenin also directly binds to MUC1 (Mucin 1), a key oncogene participating in tumor growth and metastasis." (PMID 30995775, 2019). "This construct had higher avidities to both MUC1-positive tumor cells and CD16-positive immunocytes, tethered the two types of cells together, and significantly enhanced the antitumor cytotoxicity in vitro." (PMID 30699986, 2019). "To this end, we used ELISPOT to assess IFN-γ production in response to the MUC1 vaccine in tumor-draining lymph nodes (TDLNs) of tumor-bearing mice from the untreated, vaccine alone, indomethacin alone, and indomethacin + vaccine mice." (PMID 31693710, 2019). "There were correlations between expression of (MUC1/C, D, and Z) isoforms and advanced stages, less tumor differentiation, and lymph node metastasis." (PMID 31470870, 2019). "Having identified that indomethacin improved the efficacy of the MUC1 vaccine, we next sought to determine the relative anti-tumor effects of vaccine + indomethacin compared to vaccine or indomethacin treatment alone." (PMID 31693710, 2019). "A high level of MUC1 expression was associated with CRC in the rectum, deeper invasion, lymph node metastasis, distant metastasis, advanced tumor stage, and lymphatic invasion." (PMID 31933627, 2019). "Mucin1 (MUC1) is a tumor marker overexpressed in almost all adenocarcinomas, making it a potentially important therapeutic target." (PMID 30699986, 2019).
tumor (continued). "We also performed a chromium release assay using the same effector lymphocytes isolated from vaccinated tumor-bearing MUC1.Tg mice." (PMID 31693710, 2019). "Results from this study demonstrated that combining indomethacin with the MUC1 peptide vaccine results in a significant decrease in tumor burden compared to either single treatment arm." (PMID 31693710, 2019). "Human adenocarcinomas overexpress tumor-associated transmembrane mucins, such as MUC1 and MUC4, and are associated with tumor progression by enhancing their role in cell growth and survival." (PMID 31430935, 2019). "By binding T antigen on MUC-1, Gal-3 promotes adhesion of tumor cells to the endothelium in breast and prostate cancer." (PMID 31195728, 2019). "Recent studies have demonstrated a new role of MUC1 as a metabolic modulator to reprogram tumor cells’ metabolism, mostly due to the exceptional signaling and transcriptional activity of its cytoplasmic tail (CT)." (PMID 31468283, 2019). "In mice implanted with HeLa229 TR/CRISPR cells, paclitaxel monotherapy significantly inhibited tumor growth and recurrence, suggesting that silencing of MUC1 sufficiently increased sensitivity of tumors to paclitaxel." (PMID 31772161, 2019). "MUC1 coordinates invasive growth of tumor cells, triggers EMT process and participates in cancer metastasis, which is associated with poor prognosis." (PMID 31666098, 2019). "Treatment with TAB004 + Lip-MSA-IL-2 resulted in significantly improved survival and slower tumor growth compared to controls in MUC1.Tg mice bearing an orthotopic PDA.MUC1 tumor." (PMID 31114758, 2019). "In cancer cells, MUC1 is either hypo-glycosylated or aberrantly glycosylated, resulting in the exposure of tumor-specific peptide or carbohydrate epitopes." (PMID 30699986, 2019). "Previously, we have demonstrated the effectiveness of MUC1-directed tumor vaccines in colorectal, pancreatic, and breast cancer models; however, immunosuppression within the tumor microenvironment hindered the effectiveness of the vaccine." (PMID 31114758, 2019). "JeKo-1/SPN and JeKo-1/MUC1 cells, formed approximately half the number of T cell clusters as JeKo-1/NT cells even in isotype control conditions, indicating that SPN and MUC1 repel spontaneous tumor cell/T cell contacts that occur in co-culture conditions." (PMID 31882897, 2019). "Meanwhile, MUC1 is highly expressed, the adhesion of tumor cell to peritoneum and peritoneal dissemination are promoted." (PMID 31666098, 2019). "Our previous studies indicated that IDO, one of the major players in immune tolerance but also in tumor progression, metastasis, and angiogenesis, is overexpressed in MUC1-expressing PDA." (PMID 31114758, 2019). "We were able to observe effective tumor cell killing only when the MTag.MUC1 tumor cells had been pre-treated with 100 μM indomethacin." (PMID 31693710, 2019). "The exact glycan structures of exosomal MUC1 will be future research focus, as well as their pathobiological functions in tumor microenvironment and tumor immunity." (PMID 30646616, 2019). "As a clinical indication for this obstacle to vaccine efficacy, in the trial evaluating the TG4010 Muc-1 vaccine in lung cancer only patients whose tumor expressed low levels of PD-L1 had a marked benefit in progression-free survival." (PMID 30723469, 2019). "Taken together, these results indicate that Tadalafil and polyICLC/MUC1 vaccine reshape the tumor microenvironment, lowering the immune suppressive populations and increasing the number of activated T cells." (PMID 31214178, 2019). "The glycans of MUC1 have been suggested as ligands for galectins and/or Siglecs expressed on the surface of lymphocytes, which trigger the apoptosis of tumor infiltration lymphocytes." (PMID 30646616, 2019). "The mucin, MUC1, is highly correlated with cell survival, invasion, and the metastatic ability of tumor cells." (PMID 30657763, 2019).
tumor (continued). "For example, PankoMab is a humanized monoclonal antibody that recognizes the tumour-specific epitope of MUC1 and is currently undergoing phase II trials for ovarian cancer." (PMID 31514468, 2019). "Together, these data indicated that combinational therapy was more effective at delaying MUC1+ tumor growth than either single therapy arm." (PMID 31693710, 2019). "Our observation is supported by the required role of macrophages in the anti-MUC1 tumor response in vivo." (PMID 31114758, 2019). "Blocking of radiolabeled mAb by its specific hu(TA)MUC1-glycopeptide prevented binding to tumor tissue demonstrating again the antigen specificity of GGSK-1/30 for hu(TA)MUC1." (PMID 31588183, 2019). "To assess any effects on the proliferation of tumor cells, we vaccinated tumor-bearing mice with the MUC1 peptide vaccine, and isolated effector lymphocytes from the TDLNs." (PMID 31693710, 2019). "Muc-1 is overexpressed and aberrantly glycosylated in many cancers, where it has been documented to play an important role in inflammation and tumor progression." (PMID 31337812, 2019). "Our results indicated that indomethacin in combination with the MUC1 vaccine resulted in a significant reduction in tumor burden." (PMID 31693710, 2019). "Malamas and his colleagues showed that 223Ra significantly enhanced T cell-mediated lysis of each tumor type by CD8+ cytotoxic T lymphocytes (CTLs) specific for MUC-1, brachyury, and CEA tumor antigens." (PMID 31779154, 2019). "MUC1 was shown to play an oncogenic role in regulation of self-renewal of CSCs in a variety of tumor cells." (PMID 31772161, 2019). "Next, we wanted to determine if indomethacin improves the efficacy of the MUC1 vaccine by increasing the immune response to MUC1+ tumor cells." (PMID 31693710, 2019). "The tumor-promoting function of p120ctn is regulated by MUC1, another well-known member of the MUC family, which is structurally similar to MUC16." (PMID 30795761, 2019). "It is also reported that depletion of soluble MUC1 from the tumor supernatants reversed the inhibitory effects on T cells." (PMID 31514488, 2019). "Several studies have focused on exploring the effects of glycosylation on the interactions between the antibody and its target, including tumor-specific glycosylation of MUC1, which is important in antigen recognition by MUC1-specific antibodies." (PMID 31667366, 2019). "Immunologically, this trial also confirms the positive immunomodulation of Tadalafil in patients with recurrent HNSCC and suggests an adjuvant effect of the anti-tumor vaccine MUC1/polyICLC." (PMID 31214178, 2019). "DCs were stimulated with protamine/mRNA and loaded with tumor-associated antigens NY-ESO-1, MAGE-C2 and MUC1." (PMID 31727154, 2019). "Then, effector lymphocytes isolated from TDNLs of vaccine-treated tumor-bearing mice were added to the Indomethacin treated or untreated Mtag.MUC1 cells at 50:1 and 25:1 effector:target ratios." (PMID 31693710, 2019). "This construct was able to recruit more CD16-positive cells around MUC1-positive tumor cells and enhanced the antitumor cytotoxicity." (PMID 30699986, 2019). "Taken together, these data suggest that underglycosylated MUC1 is an immunogenic tumor specific antigen in recurrent HNSCC." (PMID 31214178, 2019). "The plates were washed to remove the lymphocytes, and 3H-thymidine incorporation into the MTag.MUC1 tumor cells was evaluated." (PMID 31693710, 2019). "Our lab has previously demonstrated the effectiveness of MUC1-directed tumor vaccines in breast, colorectal, and pancreatic cancer models." (PMID 31693710, 2019). "Taken together, these results confirm a beneficial action of Tadalafil and possibly MUC1/polyICLC vaccine to the tumor macro-environment." (PMID 31214178, 2019). "A bispecific aptamer made of MUC1 and CD16 aptamer should, in principle, tether together CD16-positive immunocytes and MUC1-positive tumor cells." (PMID 30699986, 2019).
tumor (continued). "Both mouse models used here mimic the development of the human tumor, including similarities in MUC1 expression, the native immune responses against MUC1 as tumors progress, and the immune suppressive microenvironment within the developing tumor." (PMID 31114758, 2019). "Siglec-7 inhibits NK cell lysis and the mucin MUC1 modulates the tumor immunological microenvironment through engagement of the lectin Siglec-9." (PMID 31430935, 2019). "When injected into human TNBC (HCC70) tumor-bearing mice or the PyVMT.MUC1 transgenic mice (that develop spontaneous mammary gland tumors), TAB004 accumulated only in the tumor, but not in any other organs." (PMID 31178870, 2019). "We have previously shown that a vaccine consisting of MUC1 core peptides stimulates a tumor-specific immune response." (PMID 31693710, 2019). "Proton radiation and photon radiation upregulate surface cell molecules, such as ICAM1, HLA, the tumor-associated antigens MUC-1 and CEA, and calreticulin, to comparable extents, increasing the killing of tumor tissue by T cells." (PMID 30487462, 2018). "This led to the belief that peptide antigens based on the MUC1 TR sequences would induce tumour-specific adaptive immune responses." (PMID 29784646, 2018). "Here, we investigated the immunomodulatory impact of MVs carrying the MUC1 tumor glycoantigen (MVsMUC1) as immunogen formulation on clinical grade DCs grown in X-VIVO 15 (X-DCs)." (PMID 30455687, 2018). "Previously monoclonal antibody therapy directed at MUC-1 from normal tissues was ineffective but recent advancements in targeting tumor Muc1 has been promising in monoclonal antibody studies and CAR-T cell directed therapy." (PMID 30249178, 2018). "Tumour-bearing MUC1 transgenic mice treated with anti-PD-L1 antibody (21-day post tumour injection) showed increased survival and T-cell infiltration within the tumour, but induction of MUC1-specific antibodies was low." (PMID 29784646, 2018). "Several Phase I/II trials injecting autologous dendritic cell (AuDC) loaded with MUC1 as a peptide, mRNA or fused to tumour cells have been reported." (PMID 29784646, 2018). "We have recently shown that MV up-take by DCs allows cross-presentation of the MUC1 tumor glycoantigen by triggering a faster alkalinization of DC phagosomal compartment." (PMID 30455687, 2018). "Here, we assessed MUC1 expression by immunohistochemistry using tumor samples from patients with biopsy-proven NSCLC." (PMID 30479696, 2018). "Recently, antibodies generated based on the glycosylation differences of normal and tumor Muc1 have been advanced into clinical with promising efficacy." (PMID 29357376, 2018). "We used univariate analysis to compare MUC1 expression levels versus age, sex, smoking history, and tumor stage." (PMID 30479696, 2018). "TAB004 specifically recognizes the hypoglycosylated tumor form of MUC1 while sparing recognition of MUC1 on normal epithelial cells." (PMID 29685122, 2018). "To next ensure that our MUC1-targeted T cells retained effector function in the suppressive tumor microenvironment, we paired our CAR with a chimeric receptor designed to harness and invert the inhibitory effects of tumor-produced IL4." (PMID 29747685, 2018). "Delivery of the tumor antigens by MVs also modulate cross-presentation of those tumor glycosylated antigens such as MUC1 that are thought to induce only a tolerogenic CD4+ T cell response, although being relevant for tumor targeting." (PMID 30455687, 2018). "MVA has been used to generate a number of vaccines carrying specific antigens overexpressed in tumor cells including 5T4, mucin 1 (MUC1) and prostate-specific antigen (PSA)." (PMID 30257488, 2018). "Results showed that significantly higher expression of MUC1 was associated with FIGO stage (P = 0.004), tumor grade (P = 0.01), serum CA125 (P = 0.005), and PFS (P = 0.006), OS (P = 0.019)." (PMID 30518424, 2018).
tumor (continued). "Poly lactic-co-glycolic acid nanoparticles (PLGA NPs) conjugated to a tumor specific MUC1 antibody, TAB004, was used as a nanocarrier for targeted delivery into human PDA cell lines in vitro and in PDA tumors in vivo." (PMID 29685122, 2018). "Specifically, two tumour antigens expressed in carcinomas are Tn and sialyl-Tn; these structures are present in many mucin-type glycoproteins including Muc1." (PMID 30038662, 2018). "Mucin-1 (MUC1), a transmembrane glycoprotein that plays a critical role in tumor progression and metastasis in PDA." (PMID 29467938, 2018). "Their tumor selectivity was mediated by MUC1 hypoglycosylation which enabled the scFv to access the protein." (PMID 30483473, 2018). "We have to admit that this experiment only shows that the vaccine used in mouse models produced specific killing of human MUC1, with the role of inhibiting tumor growth." (PMID 29558459, 2018). "MUC1 was significantly elevated in tumor sections (p = 0.0074), but its expression level did not correlate with the IS of the Tn antigen (r = 0.0208)." (PMID 30115016, 2018). "In vitro, the Muc1-Bi bispecific antibodies can recruit Natural Killer (NK) cells to drive potent and specific cell killing of Muc1-overexpressing tumor cells." (PMID 29357376, 2018). "In fact, results of several immunotherapy trials have shown that it is possible to use different antigen vectors to trigger an efficient T cells response to tumor associate antigens such as CEA, MUC-1, k-ras/mut in mCRC patients." (PMID 29755670, 2018). "In vitro assays suggest that NK cells can exert MUC1 antibody-dependent cytotoxicity toward tumor cells, although the antitumor efficacy of ADCC has not been confirmed in vivo in cancer patients." (PMID 29857542, 2018). "In xenograft model, the Muc1-Bi bispecific antibodies can suppress tumor growth in the presence of human peripheral blood mononuclear cells (PBMC)." (PMID 29357376, 2018). "As a functional role, the MUC1 precipitates in the tumor growth, tumorigenicity, and resistance to apoptosis, and it relates to poor-prognosis of the tumors." (PMID 29342882, 2018). "Another protein, mucin 1 is encoded by MUC1, with differential glycosylation activities in normal and tumor cells." (PMID 30271341, 2018). "Because immunohistochemistry showed MUC-1 positive cells in the disseminated tumors, we chose long MUC-1 peptides for the tumor-associated antigens." (PMID 30219954, 2018). "In the 23 SOCs previously studied by us, MUC16 expression was observed in 23/23 (100%) tumours, MUC1 in 20/23 (87.0%), and truncated O-glycans expression was present in 18/23 (78.3%) for Tn, 21/23 (91.3%) for STn, and 20/23 (87.0%) for T." (PMID 30011875, 2018). "T cells that received just signals 1 + 2 (2G CAR.MUC1) were similarly dysfunctional and unable to produce tumor control." (PMID 29747685, 2018). "Taken together, these data show that transgenic expression of the 4/7ICR was insufficient to protect CAR.MUC1 T cells from tumor-mediated dysfunction." (PMID 29747685, 2018). "Increased cell surface expression of MUC1 has also been shown to interfere with T-cell interactions, allowing tumor cells to evade cellular immune responses." (PMID 30479696, 2018). "The cytoplasmic tail of MUC1 has been shown to migrate into the nucleus along with transcription factors in tumor cells." (PMID 30405607, 2018). "In summary, we have investigated the immunomodulatory impact of tumor-derived MVs carrying MUC1 as immunogen in clinical grade culture condition DCs." (PMID 30455687, 2018). "Transgenic mice expressing the soluble form of Siglec-9 showed significant resistance against GBS infection and remarkable suppression of MUC1 expressing tumor proliferation." (PMID 29342882, 2018). "In PDA, MUC1 promotes tumor progression and metastasis via signaling through its cytoplasmic tail (MUC1-CT) and interacting with other oncogenic signaling molecules." (PMID 29467938, 2018).